TBK1 (TANK binding kinase 1)
Diseases named in the same sentence as TBK1 in open-access papers (continued):
Sharing a sentence is not in itself a finding about the gene and the disease.
cancer (continued). "Together, current results provided a promising TBK1 inhibitor 15y as lead compound for immune- and cancer-related drug discovery." (PMID 35587686, 2022). "Even the TANK-binding kinase 1 (TBK1) a serine/threonine kinase, is also associated with both ALS and human cancers." (PMID 36590916, 2022). "Emerging evidence suggests that TBK1 plays critical yet tissue-variable roles in the pathogenesis of cancer." (PMID 35395857, 2022). "We hope that our effort can help to stimulate the development of novel strategies for targeting TBK1 signaling in future approaches to cancer therapy." (PMID 35395857, 2022). "Many diverse studies have demonstrated that TBK1 plays a role in not only innate immunity and metabolism, but also in cancer development and progression." (PMID 35395857, 2022). "Studies suggest that TBK1 inhibition suppresses cancer development not only by directly suppressing the proliferation and survival of cancer cells but also by activating antitumor T-cell immunity." (PMID 35395857, 2022). "TBK1 is aberrantly activated in various human cancers, however, and it would be interesting to determine if the TBK1-mediated phosphorylation of DTX3L is involved in driving cancer cell survival." (PMID 35204725, 2022). "cGAS gene expression is well correlated in many cancer types, while TBK1 and IRF3 gene expression is correlated with immune cells presence and interferon response only in few specific cancer types." (PMID 35794238, 2022). "In cancer cells harboring a KRAS-activating mutation, TBK1 is observed to promote cancer cell survival and proliferation by activating both the NF-κB and mTOR1 pathways." (PMID 35395857, 2022). "Previous study demonstrated TBK1 was involved in cancer development by regulating metabolism transformation, but the mechanism was still undefined." (PMID 35637944, 2022). "TBK1 knockdown induces the activation of mTOR-p70S6K signaling and increases the sensitivity of cancer cells in bone marrow niches to docetaxel treatment as demonstrated by a xenograft model." (PMID 35395857, 2022). "In most cancer types, TBK1 functions oncogenically, serving to promote tumorigenesis through both cell-intrinsic and cell-extrinsic mechanisms." (PMID 35395857, 2022). "As is the case in normal cells, TBK1 activation in cancer cells can be stimulated by PAMPs, DAMPs, and inflammatory cytokines." (PMID 35395857, 2022). "Next, the prognostic potential of TBK1 in different types of cancer was validated by a pan-cancer analysis of 21 types of cancer via the KM plotter." (PMID 33679751, 2021). "For example, exposure to gamma-rays can directly induce the production of type III IFN (mainly IFNL1) in human cancer cell lines through the cGAS/STING/TBK1/IRF1 signaling pathway." (PMID 35046953, 2021). "Previous studies demonstrated the potential value of TBK1 as an immunotherapeutic target for the treatment of cancer." (PMID 33679751, 2021). "We further confirmed the expression of TBK1 in multiple human cancers using microarray data sets from GEO." (PMID 33679751, 2021). "The critical role of TBK1 in tumorigenesis and aberrant TBK1 expression in cancer were reported in previous studies." (PMID 33679751, 2021). "The results obtained from TIMER revealed that TBK1 expression was up-regulated in nine types of cancer, including liver hepatocellular carcinoma (LIHC), whereas it was down-regulated in only one type of cancer." (PMID 33679751, 2021). "The TLR3 agonist Poly(I:C) induced the expression of the IRF3 target genes IFNB and CXCL10 in all tested cancer cell lines suggesting that defects upstream of TBK1/IKKe render the cancer cells unresponsive to STING agonists." (PMID 33790360, 2021). "Significant changes in TANK-binding kinase 1 (TBK1) expression in cancer versus normal tissue in GEO the database." (PMID 33679751, 2021).
cancer (continued). "Recent reports showed that anti-PD-1/anti-PD-L1-based combination therapy represented a promising strategy for HCC, and targeting TBK1 boosted the efficacy of anti-PD-1/anti-PD-L1 in various types of cancer." (PMID 33679751, 2021). "We performed a survival analysis based on TBK1 mRNA expression by GEPIA in 33 types of cancer to estimate the influence of TBK1 expression on prognosis in patients with cancer." (PMID 33679751, 2021). "Numerous cancer types present the aberrant TANK-binding kinase 1 (TBK1) expression, which plays an important role in driving inflammation and innate immunity." (PMID 33679751, 2021). "Actually, persistent activation of this pathway and its downstream effectors, such as TBK1, has been connected with chronic inflammation and cancer progression." (PMID 33006365, 2020). "In HER2-mutated cancer cells, HER2 associates with STING and recruits AKT1 to phosphorylate TBK1, the downstream signaling target of STING, thereby preventing STING-TBK1 and TBK1-IRF3 interactions." (PMID 32774773, 2020). "It is known that the AKT signaling pathway plays an important role in mediating EMT and is directly activated by TBK1 in cancer cells." (PMID 30988282, 2019). "In fact, one of the most significant and top dysregulated gene networks distinguishing TBK1 WT and TBK1-mutant tumors was the cancer/cellular movement networks, including many genes involved in EMT." (PMID 31681587, 2019). "Further investigations and better inhibitors will be needed before TBK1 can be directly targeted in RAS-driven cancer in preclinical and clinical settings." (PMID 31681587, 2019). "An RNAi screen identified TANK Binding Kinase 1 (TBK1) as a top candidate synthetic lethality partner of mutant Kras in various human cancer cell lines." (PMID 31277415, 2019). "For TBK1 to be a relevant target in the clinic, it will be necessary to evaluate the therapeutic efficacy of TBK1 inhibition in preclinical cancer models." (PMID 31681587, 2019). "Suppression of TBK1 induces apoptosis of KRAS-driven cancer cells, and JAK2 inhibition of STAT3 activation results in decreased growth." (PMID 30105668, 2019). "White and colleagues reported that RalB/Sec5 activated TBK1 to promote cancer cell survival in a study focused on Ras-induced transformation." (PMID 30223576, 2018). "Future cancer studies need to consider potential effects of TBK1/IKKε inhibitors on the likely suppressive effects related to pathogen clearance and on immune system function, such as immune tolerance." (PMID 30223576, 2018). "A major breakthrough was the discovery that TBK1 is chronically activated in a variety of cancer cells, and that its activity is required for RAS-induced transformation." (PMID 29971063, 2018). "Here we review the involvement of TBK1 and IKKε in controlling different cancers and in regulating responses to cancer immunotherapy." (PMID 30223576, 2018). "In KRAS-positive cancers, TBK1 involvement in regulating Akt/mTORC1 was found in cells with a mesenchymal phenotype." (PMID 30223576, 2018). "Our findings thus expand the role of autophagy addiction in K-Ras driven cancer and show mechanistic interplay with the TBK1-NF-κB pathway." (PMID 23209807, 2012). "Together, these data describe a new high-throughput screening assay which will facilitate the discovery of small molecule TBK1/IKKε inhibitors possessing therapeutic potential for both inflammatory diseases and cancer." (PMID 22859992, 2012). "Given the interest in developing TBK1 inhibitors for cancer treatment, we need to understand in detail the consequences of loss of the pathway described here." (PMID 23209807, 2012). "However, although many excellent reviews mention inflammation when discussing the various roles of TBK1 in diseases, such as innate immunity, cancer immunity, and autophagy, specific reviews discussing its role in regulating inflammation are lacking." (PMID 40076567, 2025). "KARS activates TBK1 through RALB to promote cancer cell survival." (PMID 40478912, 2025).
cancer (continued). "Furthermore, the inhibitory effects of targeting TBK1 on cancer cell proliferation and migration were mediated by the protein kinase B (AKT)/NF-κB signaling pathway." (PMID 39744441, 2025). "TBK1’s high hazard ratio identifies it as a potential therapeutic target, aligns with recent studies proposing TBK1 inhibitors as potential anti-cancer agents." (PMID 40808675, 2025). "TBK1 is involved in various diseases, including metabolic diseases and cancer." (PMID 39744441, 2025). "In the following paragraphs, we have classified inflammation-related diseases into three categories and discussed the mechanisms of TBK1 in immune-mediated inflammatory diseases (IMIDs), metabolic inflammatory syndromes (MIS), and inflammation-associated cancers." (PMID 40076567, 2025). "TBK1’s participation in the inflammatory response not only underscores its multifaceted roles but also presents potential avenues for therapeutic intervention in cancer." (PMID 38567349, 2024). "In cancer cells with HER2 mutations, HER2 combines with STING and recruits the kinase AKT1 to phosphorylate TBK1, thus preventing the interaction between STING‐TBK1 and TBK1‐IRF3, ultimately shielding cancer cells from host antitumor immunity." (PMID 38525112, 2024). "TBK1 influence the cellular milieu and potentially impacting cancer progression." (PMID 38567349, 2024). "TBK1 has been identified through genome-wide screening as a site of carcinogenesis with upregulated expression in numerous tumors, correlating with poor prognosis, rendering it an appealing target for robust cancer suppression." (PMID 39161768, 2024). "Our understanding of TBK1 upstream signaling in cancer and other diseases remains incomplete." (PMID 39279883, 2024). "Considering that BACH1 promotes cancer progression, the negative regulatory role of TBK1 on BACH1 found in the present study may be modulated in cancer cells to a positive regulatory role, promoting BACH1 protein accumulation." (PMID 38673728, 2024). "This function is observed in multiple cancer cell lines such as A549, U937 and HeLa and could be an important mechanism by which TBK1 promotes cancer cell survival." (PMID 39279883, 2024). "In addition, TBK1 is also known to activate transcriptionfactors responsible for epithelial-mesenchymal transition (EMT) whichcan lead to cancer metastasis." (PMID 39289178, 2024). "Additionally, TBK1’s involvement in oncogenicpathways links it to cancer progression and survival, making it apotential target for therapeutic intervention." (PMID 39289178, 2024). "Here we will focus on TBK1 activity specifically in cancer cells." (PMID 39279883, 2024). "A pan-cancer analysis revealed that high activation of the cGAS-STING pathway and its downstream signaling components such as TBK1 and IRF3 is associated with reduced immune cell infiltration in the TME and poor prognosis for colorectal and gastric adenocarcinomas." (PMID 38999073, 2024). "TBK1 promotes cancer cell survival and proliferation by phosphorylating mTOR at Ser 2159." (PMID 39061024, 2024). "Tank Binding Kinase 1 (TBK1) is one such kinase, which is known to be activated on the centrosomes during mitosis and is also often overexpressed in certain cancer types." (PMID 38059900, 2024). "Inhibiting TBK1 activity could potentially suppressthese cancer-promoting effects and enhance the efficacy of other anticancertreatments." (PMID 39289178, 2024). "Tumour necrosis factor (TNF) receptor-associated factor (TRAF) family member-associated NF-κB activator TANK-binding kinase 1 (TBK1), which is also known as NAK, T2K, is a serine/threonine-protein kinase that plays essential roles in cancer development and progression." (PMID 36928362, 2023). "The results revealed that TBK1 expression was upregulated in nine types of cancer, including CCA, suggesting that TBK1 may participate in the tumorigenesis and progression of several solid tumours." (PMID 36928362, 2023).
cancer (continued). "TBK1 expression is upregulated in different types of human cancers." (PMID 36988258, 2023). "Indeed, we found that inhibition of ATM led to a robust increase in the expression of cGAS, the phosphorylation of STING and TBK1 in a variety of human cancer cell lines, including HeLa, H157, H1299, A549, MDA-MB-231 and BT549." (PMID 36778120, 2023). "TBK1 plays a vital role in cancer development and progression." (PMID 36928362, 2023). "In addition to mediating the innate immune response, TBK1 also plays a critical role in cancer therapy." (PMID 35587686, 2022). "Therefore, carefully studying the roles of TBK1 in different types of cancer will help to develop a rationale for targeting TBK1 as part of an anti-neoplastic therapeutic strategy." (PMID 35395857, 2022). "Much of the current literature suggests TBK1 inhibition could be an effective way to decrease cancer cell viability and invasiveness, across a remarkable range of cancer types, excluding those arising from villin+ intestinal epithelium." (PMID 35395857, 2022). "In examining its established involvement in mitophagy and mitochondrial metabolism, we hypothesize that TBK1 may contribute to the initiation and/or maintenance of the cancer stem cell phenotype." (PMID 35395857, 2022). "We also discuss the potential molecular mechanisms of targeting TBK1 for cancer treatment." (PMID 35395857, 2022). "Future studies should evaluate the role of TBK1 in cancer stem cells and chemoresistance with the goal of determining whether pharmacologic inhibition of TBK1 can sensitize cancer stem cells to chemotherapy as a means of preventing disease relapse." (PMID 35395857, 2022). "In addition to NF-κB and mTOR, TBK1 can also promote cancer development and progression through other pathways." (PMID 35395857, 2022). "Therefore, tool molecules need to be developed urgently for further revealing TBK1 biological functions involving the correlative network of cell signals of immune response and cancer." (PMID 35587686, 2022). "Thus, the potency (e.g. IC50) and selectivity (e.g. TBK1-selective versus TBK1/IKKe dual) should be considered when choosing which TBK1 inhibitors to pursue in clinical trials for cancer therapy." (PMID 35395857, 2022). "Individual knockdown of either IKKi or TBK1 have minor effects on cell survival while simultaneous knockdown of both TBK1 and IKKi significantly inhibited cell proliferation, suggesting that simultaneously targeting both TBK1 and IKKi is necessary for the efficient shutdown of cancer cell growth." (PMID 35335873, 2022). "Although TBK1 has been proposed as a target of inflammatory, autoimmune and metabolic disorders as well as cancer, the related mechanisms remain unclear to large extent." (PMID 35587686, 2022). "The tumorigenic activity of TBK1 has been verified in several cancer models, suggesting that TBK1 may be an attractive molecular target for antineoplastic drugs." (PMID 35395857, 2022). "Thus, blocking the action of TBK1 in most cancer cells is expected to attenuate the invasive/malignant phenotype." (PMID 35395857, 2022). "Recently, the role of TBK1 has been expanded into cancers and autophagy." (PMID 36009179, 2022). "Collectively, this evidence indicated that STING may contribute to cancer-induced bone pain by activating TBK1 and NF-κB, and by promoting M1 polarization of microglia in the mPFC." (PMID 36358605, 2022). "Therefore, there is a possibility that PARP inhibitor simultaneously suppresses TGF‐β signaling through production of phosphorylated IRF3 by TBK1, and this can be one of the mechanisms of cancer cell death by PARP inhibitor." (PMID 33342034, 2021). "Furthermore, GEPIA and the KM plotter indicated the significant value of TBK1 expression as a prognostic biomarker in 17 types of cancer." (PMID 33679751, 2021).
cancer (continued). "Given that TBK1 expression and activity are enhanced in metabolic diseases and cancer, and the important role that Akt plays in these pathological conditions, identifying TBK1 as an upstream regulator of Akt reveals a potential novel approach to disrupt this signaling axis for therapeutic benefit." (PMID 34563542, 2021). "Taken together, we speculate that the catalytic activity of PARP7 can be used as a therapeutic target for regulating TBK1 kinase activity to control inflammation and cancer." (PMID 34367175, 2021). "Together with the decrease in LC3B-II after amlexanox treatment, our data indicate that TBK1 and IKKε are involved in the pro-survival effects of autophagy in cancer, which might be counteracted by the administration of IKKε/TBK1 inhibitors." (PMID 32630674, 2020). "In agreement with the concept that TBK1 loss affects antitumor immunity, studies by the Cantley and Barbie groups have reported that immune evasion and metastatic behavior are associated with the cGAS/STING/TBK1 innate immune pathway in cancer cells." (PMID 31681587, 2019). "To define the NF-κB-activating kinase responsible for aberrant NF-κΒ signaling of KRASMUT cancer cells, we stably expressed shRNAs specifically targeting IKKα, IKKβ, IKKε, and TBK1 transcripts (Chuk, Ikbkb, Ikbke, and Tbk1, respectively) in our pNGL-expressing cell lines and validated them." (PMID 29445180, 2018). "In non-cancer diseases, TBK1 has been shown to drive neuroinflammation and autoimmunity." (PMID 30223576, 2018). "An additional concern relates to whether targeting TBK1 or IKKε uniquely would be more (or less) effective for a particular cancer." (PMID 30223576, 2018). "IKKε and TBK1 are overexpressed through multiple mechanisms in various human cancers." (PMID 27145266, 2017). "TBK1’s role in cancer may be due to its involvement in regulation of cell growth and proliferation, angiogenesis and oncogenic transformation." (PMID 27145266, 2017). "Previous studies revealed that IKKε and TBK1 play a significant role in several cancers." (PMID 27145266, 2017). "A knock-out of TNFR in mice has already been repeatedly associated with reduced nociceptive responses in models of inflammatory, cancer, and neuropathic pain and might thus cover antinociceptive effects mediated by TBK1 knock-down." (PMID 25997745, 2015). "Finally, this new role of TBK1 also opens new avenues for targeting TBK1 in cancer, to induce mitotic catastrophe and cell death." (PMID 26656453, 2015). "As TBK1 and IKKε are points of convergence for both inflammatory and oncogenic signaling pathways, the further refinement of novel TBK1/IKKε inhibitors may provide powerful new therapeutic drugs for inflammatory disorders or cancer." (PMID 22859992, 2012). "In addition, both TBK1 and IKKε have been studied in the context of cancer." (PMID 40738190, 2025). "Moreover, since syntenin-1 has been reported to play a key role in cancer metastasis, we also tested if TBK1-syntenin-1 co-expression could promote A549 cells migration." (PMID 40412527, 2025). "Additionally, we utilized the quantitative phosphoproteome data of TBK1 knockout cancer cells to explore the effect of TBK1 on syntenin-1 phosphorylation and observed that the phosphorylation level of syntenin-1 serines was notably downregulated in TBK1 knockout cells compared to wild-type cells." (PMID 40412527, 2025). "However, the direct upstream kinase responsible for TBK1 activation remains elusive, which limits our comprehensive understanding of its activation mechanism and potential therapeutic application targeting TBK1-related signaling especially in cancer." (PMID 39279883, 2024). "In addition, the role of TBK1 has expanded into cancers, autophagy and ubiquitination." (PMID 38673728, 2024). "Although TBK1 is considered a target of cancer, its related mechanisms remain unclear." (PMID 36988258, 2023). "Thus, the role(s) of TBK1 in immune cells with respect to the pathogenesis of cancer are largely unknown." (PMID 35395857, 2022).